GHR (growth hormone receptor)
Description:
Receptor for pituitary gland growth hormone (GH1) involved in regulating postnatal body growth. On ligand binding, couples to the JAK2/STAT5 pathway. [Growth hormone-binding protein]: The soluble form (GHBP) acts as a reservoir of growth hormone in plasma and may be a modulator/inhibitor of GH signaling. [Isoform 2]: Up-regulates the production of the soluble Growth hormone-binding protein form (GHBP) and acts as a negative inhibitor of growth hormone signaling.
Synonyms: GHBP; GHIP
Tractability: Small molecule: an approved drug acts on it. Antibody: UniProt places it where antibodies can reach, with high confidence; its Gene Ontology location is reachable by antibodies, with high confidence; UniProt predicts a signal peptide or a membrane-spanning region; the Human Protein Atlas places it where antibodies can reach. PROTAC: UniProt records ubiquitination sites on it; ubiquitination databases record sites on it; its protein half-life has been measured. Other modalities: an approved drug acts on it.
Target class: Membrane receptor
Gene: Protein-coding gene on chromosome 5 (42,423,439 to 42,721,878, forward strand). Ensembl gene ENSG00000112964.
Subcellular location: Cell membrane; Cell membrane (Isoform 2); Secreted (Growth hormone-binding protein)
Subcellular location (Human Protein Atlas): Cytoplasmic bodies; Cytosol; Plasma membrane; Predicted to be secreted
Pathways (Reactome):
Immune System: Growth hormone receptor signaling; Prolactin receptor signaling
Gene Ontology:
Molecular function: growth hormone receptor activity; identical protein binding; lipid binding; peptide hormone binding; protein binding; protein homodimerization activity; cytokine binding; proline-rich region binding; protein tyrosine kinase activator activity; protein tyrosine kinase binding; cytokine receptor activity; protein kinase binding; protein phosphatase binding; SH2 domain binding
Biological process: cellular response to hormone stimulus; growth hormone receptor signaling pathway; hormone metabolic process; insulin-like growth factor receptor signaling pathway; positive regulation of multicellular organism growth; cell surface receptor signaling pathway via JAK-STAT; cytokine-mediated signaling pathway; positive regulation of cell population proliferation; positive regulation of MAPK cascade; positive regulation of receptor signaling pathway via JAK-STAT; regulation of multicellular organism growth; taurine metabolic process; cartilage development involved in endochondral bone morphogenesis; cellular response to insulin stimulus; hormone-mediated signaling pathway; positive regulation of cell differentiation; regulation of response to nutrient levels; response to cytokine; response to food; response to glucocorticoid; response to gravity; response to growth hormone; response to hormone; response to interleukin-1; response to peptide hormone
Cellular component: cell surface; extracellular region; growth hormone receptor complex; membrane; plasma membrane; receptor complex; cytosol; external side of plasma membrane; neuronal cell body
Genetic constraint (gnomAD): Loss-of-function variants: 16 observed, 37.36 expected, observed/expected ratio (o/e) 0.43, 90% interval 0.29 to 0.65. The upper end of that interval is the gene's LOEUF score, 0.65, which puts it in group 2 of 6, group 1 being the genes least tolerant of losing a copy. Missense variants: 540 observed, 551.16 expected, observed/expected ratio (o/e) 0.98, 90% interval 0.91 to 1.05. Synonymous variants: 202 observed, 200.2 expected, observed/expected ratio (o/e) 1.01, 90% interval 0.9 to 1.13.
Homologues: Orthologues: chimpanzee GHR (99% identical), macaque GHR (94% identical), pig GHR (85% identical), rabbit GHR (84% identical), dog GHR (83% identical), guinea pig GHR (73% identical), rat Ghr (70% identical), mouse Ghr (70% identical), tropical clawed frog ghr (45% identical), zebrafish ghra (33% identical), zebrafish ghrb (27% identical), zebrafish il11ra (9% identical), and 1 more. Paralogues in human: PRLR (20% identical), IL6ST (13% identical), IL12RB2 (11% identical), LIFR (11% identical), IL31RA (10% identical), IL23R (10% identical), OSMR (10% identical), LEPR (10% identical), CSF3R (10% identical), IL12RB1 (9% identical), IL27RA (9% identical), CRLF2 (8% identical), and 11 more.
Diseases named in the same sentence as GHR in open-access papers:
GHR is named in the same sentence as 203 diseases in open-access papers, as found by Europe PMC text mining. Sharing a sentence is not in itself a finding about the gene and the disease. The quoted sentences say what the papers report.
Laron syndrome (97 papers, 2007 to 2026). Laron syndrome is a congenital disorder characterized by marked short stature associated with normal or high serum growth hormone (GH) and low serum insulin-like growth factor-1 (IGF-I) levels which fail to rise after exogenous GH administration. "Laron syndrome was first described as being associated with a pathological autosomal recessive GH receptor (GHR) gene variant; other genetic causes of SPIGFD have since been described." (PMID 40626687, 2026). "Genetic defects involved in GHI include two main categories: Laron syndrome, associated with defects within GHR gene, and alterations that cause defects in the GH intracellular signaling pathway, such as mutations of STAT5B, IKBKB, STAT3, IL2RG and PIK3R1." (PMID 40868191, 2025). "For instance, in Laron’s syndrome, which is caused by a genetic mutation in GHR, IGF-I levels are low despite high GH levels due to GHR dysfunction." (PMID 38596224, 2024). "Conversely, primary GH insensitivity, known as Laron Syndrome (LS), in most cases is due to homozygous inactivating mutation(s) of the GHR gene." (PMID 38831184, 2024). "Accordingly, in conditions of GH insensitivity due to deficiency of the growth hormone receptor (human Laron syndrome), growth retardation and an increased accumulation of adipose tissue are displayed." (PMID 38960990, 2024). "The best characterized, “classic” form of SPIGFD is Laron syndrome, caused by mutations in the GHR gene." (PMID 37805563, 2023). "Delayed puberty or an increase in the duration of the entire puberty process is frequently reported in patients with Laron syndrome who have a resistance to GH due to mutations in the GHR gene." (PMID 37685880, 2023). "Pathogenic variants in the GHR gene can result in structural and functional defects in the GHR protein, leading to Laron Syndrome (LS) with the primary clinical manifestation of short stature." (PMID 37474955, 2023). "In humans, Laron syndrome, caused by the mutation of the growth hormone receptor (GH-R) gene, is characterized by a remarkable degree of protection from age-related diseases such as cancer and diabetes." (PMID 37441495, 2023). "The first cause of GHI is Laron syndrome, caused by a homozygous mutation of the gene encoding the GH receptor (GHR), resulting in complete GHI." (PMID 35949366, 2022). "Laron syndrome (LS) is a type of dwarfism that results from mutation of the GH receptor (GHR) gene, leading to GH resistance and short stature as well as a number of metabolic abnormalities." (PMID 35626664, 2022). "Laron syndrome is a rare, genetic, growth hormone insensitivity disorder caused by mutations in the growth hormone receptor gene." (PMID 36721555, 2022). "Mutations in the GHR gene cause growth hormone insensitivity syndrome (Laron’s syndrome), as well as partial growth hormone sensitivity." (PMID 35627241, 2022). "Laron syndrome (LS) is an inherited autosomal recessive disorder caused by molecular defects of the GH receptor (GHR) gene, leading to congenital IGF1 deficiency." (PMID 36291127, 2022). "Laron syndrome (LS) is a genetic disorder that results from the mutation or deletion of the growth hormone receptor (GHR) gene, thereby leading to impaired IGF1 production and dwarfism." (PMID 36291127, 2022). "Laron syndrome (LS), or primary GH insensitivity, is a recessively transmitted genetic form of dwarfism caused by the deletion or mutation of the GH receptor (GHR) gene, leading to congenital IGF1 deficiency." (PMID 34769292, 2021). "In this context, Laron syndrome, characterized by a loss of function mutation in the growth hormone receptor gene, leading to high levels of GH combined with low levels of IGF-1, is particularly instructive." (PMID 34948002, 2021). "Laron syndrome (LS) is an autosomal recessive genetic disease mainly caused by mutations in the human growth hormone receptor (GHR) gene." (PMID 34803486, 2021).
Laron syndrome (continued). "Homozygous mutations in the GHR gene have been associated with Laron dwarfism (OMIM # 262500), increased responsiveness to growth hormone, and growth hormone insensitivity (OMIM # 604271)." (PMID 34614013, 2021). "Laron syndrome (LS) is a severe growth disorder caused by GHR gene mutation or post-receptor pathways defect." (PMID 33912130, 2021). "Laron syndrome (LS) is a type of dwarfism that results from the mutation of the growth hormone receptor (GHR) gene, leading to congenital IGF1 deficiency." (PMID 34204736, 2021). "In the mouse model discussion, homozygous or compound heterozygous mutations in GHR are responsible for GH insensitivity syndrome, also known as Laron syndrome (OMIM 262500)." (PMID 34680948, 2021). "The growth pattern of body and organ in pigs with growth hormone receptor (GHR) knockout mutations are similar to those in human with Laron syndrome, which is a rare and autosomal recessive disorder caused by loss-of-function mutations in the GHR gene." (PMID 33461495, 2021). "Loss-of-function mutations of the growth hormone receptor (GHR) gene cause the rare autosomal recessive hereditary disease Laron syndrome (LS), which is characterized by short stature, obesity, and transient juvenile hypoglycemia." (PMID 33029223, 2020). "These conditions result from: (i) a GH releasing hormone-receptor (GHRH-R) defect; (ii) GH gene deletion (isolated GH deficiency, IGHD); (iii) GH receptor (GHR) gene deletion or mutation (Laron syndrome); (iv) IGF1 gene deletion or IGF1R gene defect." (PMID 33182502, 2020). "Laron syndrome (LS) is a rare genetic endocrinopathy that results from mutation of the growth hormone receptor (GH-R) gene and is typically associated with dwarfism and obesity." (PMID 33182502, 2020). "Laron syndrome (LS) is a rare autosomal recessive growth retardation from a mutation in the growth hormone receptor (GHR) gene leading to defective GHR, growth hormone insensitivity and eventual low levels of insulin-like growth factor type 1 (IGF-1)." (PMID 32296486, 2020). "Laron syndrome (LS) is a genetic type of dwarfism that results from mutation of the growth hormone receptor (GHR) gene, and is the best characterized entity under the spectrum of the congenital IGF1 deficiencies." (PMID 31320996, 2019). "Laron syndrome (LS), or primary growth hormone resistance, is a genetic type of dwarfism that results from mutation of the growth hormone receptor (GHR) gene and that is transmitted in an autosomal recessive fashion." (PMID 31320996, 2019). "Classical cases of growth hormone insensitivity (GHI) are usually due to mutations in GH receptor (GHR), which is a member of cytokine-hematopoietin family of receptors that do not show any intrinsic kinase activity." (PMID 30109213, 2018). "Laron syndrome (LS) is a rare, autosomal recessive disorder in humans caused by loss-of-function mutations of the growth hormone receptor (GHR) gene." (PMID 29678421, 2018). "Loss of function in GHR genes, predominantly owing to mutations in their extracellular domains, results in Laron syndrome." (PMID 29482569, 2018). "Currently, the pathogenesis of Laron syndrome has been confirmed as mutations of the GH receptor (GHR)." (PMID 29482569, 2018). "Laron syndrome is an autosomal disease resulting from mutations in the growth hormone receptor (GHR) gene." (PMID 29482569, 2018). "Mutations localized in the Growth Hormone Receptor (GHR) gene are often associated with the pathogenesis of Laron Syndrome, an autosomal recessive hereditary disorder characterized by severe growth retardation." (PMID 29025428, 2017). "In acromegaly, a condition of GH excess, there is low body fat with insulin resistance, and in Laron’s syndrome, due to an inactivating mutation in the growth hormone receptor (GHR), there is high body fat with insulin sensitivity." (PMID 28713554, 2017).
Laron syndrome (continued). "A population of Ecuadorian individuals suffering from Laron syndrome, carried mutations in the growth hormone receptor (GHR) gene which leads to severe GHR and IGF-1 deficiency." (PMID 25964779, 2015). "Laron syndrome is a rare disease caused by mutations of the growth hormone receptor (GHR), inheriting in an autosomal manner." (PMID 26511035, 2015). "A cohort study of the Laron syndrome, in which GH receptor (GHR) is deficient and serum IGF-I levels are extremely low, demonstrated that the prevalence of cancer and diabetes was drastically decreased." (PMID 26448623, 2015). "In our study, we chose to knock out the pig GHR gene at exon 6 to generate a Laron syndrome disease model mainly because exon 6 encodes part of the extracellular domain of GHR, thereby this deletion would abrogate the function of GHR by causing a frame shift." (PMID 26511035, 2015). "Individuals with Laron syndrome who carry mutations in the growth hormone receptor (GHR) gene that lead to severe congenital IGF-1 deficiency with decreased insulin/IGF-1 signaling (IIS) exhibit reduced prevalence rates of acne, diabetes and cancer." (PMID 21699736, 2011). "We present the outcome of eight-year recombinant IGF-1 (rIGF-1) replacement in a girl with Laron type dwarfism caused by an R217X mutation of the gene encoding for GHR, who developed hypothyroidism during treatment." (PMID 21745362, 2011). "Primary GH resistance or GHIS, also known as Laron syndrome, is a hereditary disease caused by deletions or mutations in the GHR gene or the post-receptor mechanisms." (PMID 21745362, 2011). "The genetic analysis showed that the patient was homozygous for the R217X mutation in the growth hormone receptor gene, which is characteristic of Laron syndrome." (PMID 21745362, 2011). "The genetic analysis showed that the patient was homozygous for the R217X mutation of the GHR gene, which is characteristic in patients with Laron syndrome." (PMID 21745362, 2011). "Growth hormone (GH) receptor (GHR) mutations give rise to GH-resistance (Laron syndrome)." (PMID 42290866, 2026). "In humans, extensive studies in Ecuadorians with Laron Syndrome (LS), caused by germline inactivating mutations in the GH receptor (GHR), demonstrate improved insulin sensitivity, resistance to diabetes and cancer, enhanced memory function, and decreased pro-aging signaling." (PMID 41350448, 2025). "Given that cancer is a primary cause of death and a major health risk in upcoming long-term spaceflight, understanding the physiological underpinnings of GHR mutations associated with Laron syndrome could lead to potential anti-cancer therapies." (PMID 39039045, 2024). "Furthermore, this is a common phenotype in patients with Laron syndrome, a genetic disorder caused by a mutation of the GHR gene." (PMID 37685880, 2023). "Laron syndrome is a fully penetrant autosomal recessive disease caused by exon deletion or mutations of the GHR, leading to the disruption or alteration of the GH-binding site or failure to express the GHR on the cell surface." (PMID 37008935, 2023). "In humans, a disease called Laron syndrome is caused by defects in GHR." (PMID 34954140, 2022). "Genetic variants of the GHR gene in patients with Laron Syndrome." (PMID 33912130, 2021). "Recently, Laron syndrome has been mimicked in porcine models with GHR knockout mutations." (PMID 34948002, 2021). "In order to investigate whether the GH insensitivity is due to changes in GHR receptor biology, as occurs in Laron syndrome (due to GHR mutation) or during fasting (downregulation of GHR), we quantified hepatic GHR, but its levels were unchanged." (PMID 32573078, 2020). "Similarly, mutations in the growth hormone receptor (GHR) can lead to Laron syndrome (LS), one of the several disorders that are collectively called growth hormone insensitivity syndrome (GHI)." (PMID 32935225, 2020).